ABL1 (ABL proto-oncogene 1, non-receptor tyrosine kinase)
Diseases named in the same sentence as ABL1 in open-access papers (continued):
Sharing a sentence is not in itself a finding about the gene and the disease.
tumor (300 papers, 2004 to 2026). "The histopathological and molecular features of the tumor, including mutations in ABL1, CCND1, CSF1R, FGFR4, KDR, and MALAT1-GLI1 fusion, are elucidated and discussed in the context of diagnostic, prognostic, and therapeutic considerations." (PMID 38732067, 2024). "We used TIMER to further study the association between ABL1 and the level of tumor immune cell infiltration." (PMID 34484330, 2021). "We aimed to evaluate the specific biological function of ABL1 in HCC through bioinformatics methods to identify ABL1-related pathways and determine the association between ABL1 and tumor immunity." (PMID 34484330, 2021). "Sequencing identified germline and tumor amplified, expressed, high-impact druggable variants in two genes (ABL1, NOTCH1) and expressed, medium impact variants in three additional genes (MDM4, PAK4, MAP4K5)." (PMID 31208434, 2019). "By binding VEGF-A to NRP1, GIPC1 mediates the interaction between NRP1 and ABL1, which activates tyrosine kinase activity and associates with integrins, leading to induce tumor growth." (PMID 26209534, 2015). "Similarly, we identify mutations in both tumor-suppressor genes, e.g., ABL1, JAK2, MAP2K1, and KIT, from poor responders in CML, suggesting that these are two of the key mechanisms by which tumor cells evolve to acquire drug resistance." (PMID 38459554, 2024). "Additionally, the ABL1 gene regulates cytoskeletal dynamics and is linked to tumor drug resistance and cell migration." (PMID 38988712, 2024). "A major characteristic of BCR::ABL1 is the induction of genomic instability associated with its leukemogenesis through the promotion of non-conservative DNA repair pathways and consequent increase in tumor mutation burden." (PMID 38067214, 2023). "This comparison is possible because we corrected the tumor burden value observed in the RNA method by the disease level of each patient at that time multiplying the variant allele frequency of the mutation by the BCR::ABL1/ABL1 ratio." (PMID 35906470, 2022). "In addition, we also observed that ABL1 expression was significantly correlated with monocytes, tumor-associated macrophages, M1/M2 macrophages, NK cells, and dendritic cells." (PMID 34484330, 2021). "We hypothesized that the ABL1-MS1 polymorphism loses its ability to suppress the ABL1 expression during tumor formation." (PMID 33952249, 2021). "As compared to control, ABL1 depletion caused a significant reduction in tumor volume." (PMID 32850446, 2020). "However, despite these difficulties, ponatinib induced tumor regression in all treated mice, indicating that the mechanism of D/T + nilotinib resistance may involve ABL1 or ABL2 mutation." (PMID 33122628, 2020). "The TCA cycle pathway emerged as the most significant at day 21 post-BCR::ABL1 induction, consistent with the Warburg effect observed in tumor cells." (PMID 40221405, 2025). "Despite this, matching epithelial and mesenchymal subtype kinase activities were found between tumor and cell profiles, e.g. mesenchymal cells displayed significantly higher ABL1 kinase activity, in line with the stromal Phos3 profiles." (PMID 38650175, 2024). "Taken together, these findings in tumor cells suggest that ABL1-mediated FOXM1 phosphorylation and stabilization contribute to tumor development by promoting cell proliferation and suppressing tumor cell apoptosis." (PMID 39060421, 2024). "The FOXM1 expression, the level of ABL1 phosphorylated at Y412 (pY412), and Ki67 level were significantly increased in tumor tissues compared to paracarcinoma tissues, indicating an essential role of ABL1 activation in FOXM1 expression and cell proliferation." (PMID 39060421, 2024). "Abelson tyrosine-protein kinase 1 (ABL1) belongs to the ABL family of tyrosine kinases which has been reported to promote tumor progression and metastasis in a variety of solid tumors." (PMID 38584839, 2024).
tumor (continued). "Here we show that normal ABL1 kinase plays a tumor suppressor role in hematological malignancies induced by AML1-ETO and NUP98-PMX1 and modulates the response to phosphatidylinositol-3 kinase (PI3K) and DNA damage response (DDR) inhibitors." (PMID 36959186, 2023). "For example, ABL1 was found to be overexpressed and activated in numerous solid tumors presumably to promote tumor cell growth and invasion." (PMID 36959186, 2023). "In conclusion, we showed that ABL1 kinase plays a tumor suppressor role in hematological malignancies induced by AML1-ETO and NUP98-PMX1 and modulates the response to PI3K and/or DDR inhibitors." (PMID 36959186, 2023). "In vitro analysis revealed profound reduction of T cell proliferation, differentiation, cytokine release and killing of tumor cells upon application of BCR::ABL1 TKI with blinatumomab." (PMID 35551463, 2022). "Hence, a possible tumor suppressive mechanism of Ikaros is to activate the expression of a miRNA (hsa-miR-663a) that represses ABL1 expression to restrict cell growth, and mutation in IKZF1 in Ph+ B-ALL could relieve such oncogene repression by reduced tsmiR levels." (PMID 36278683, 2022). "A clear trend towards faster tumor cell engraftment and proliferation was obvious in BCR::ABL1-mutated samples (four out of five), as well as T-ALLs." (PMID 35011712, 2022). "The multiplex ddPCR assay was developed using tumor cell lines positive for the tumor associated antigens (TAA: WT1, PRAME, BIRC5), with homeostatic ABL1." (PMID 36248870, 2022). "We observed that all CRISPR/Cas treatment modalities targeting the BCR/ABL1 fusion gene were beneficial with respect to the tumor volume, as assessed 30 days post tumor electroporation." (PMID 35739111, 2022). "The TAA/ABL1 mRNA ratios in the tumor cell line-spiked samples were highly reproducible, with a CV of 0.05 and 0.11 for WT1/ABL1, 0.1 and 0.21 for PRAME/ABL1, and 0.12 and 0.21 for BIRC5/ABL1." (PMID 36248870, 2022). "Five NCI60 tumor cell lines have the defective ABL1 gene; with these tumor cell lines having a mean GI50defective response nine-fold higher than GI50wild-type (p = 6.91e-3)." (PMID 33909629, 2021). "The high ABL1 expression significantly influences the immune cell infiltration and immune checkpoint expression in the tumor microenvironment in HCC." (PMID 34484330, 2021). "Subsequent studies have shown that ABL1 is abnormally expressed in a variety of tumors and plays a crucial role in tumor proliferation, migration, invasion, and metastasis." (PMID 34484330, 2021). "Further, the effects of knockout of ABL1 in tumor and the molecular mechanisms of activated and suppressed downstream signaling pathways were assayed to elicit the mechanisms involved in CRC carcinogenesis." (PMID 32850446, 2020). "In order to examine the involvement of ABL1 in regulating CRC tumor growth, we inoculated HCT-116 cells infected with shCtrl (NC group) or shABL1 (KD group) into BALB/c nude mice." (PMID 32850446, 2020). "It has been reported that ABL1 regulates TGF-β signaling, which is associated with tumor progression by modulating angiogenesis in CRC, resulting in poor prognostic outcome." (PMID 32850446, 2020). "AZD0424, an oral inhibitor of Src and ABL1, has shown evidence of anti-tumour activity in pre-clinical studies." (PMID 29438361, 2018). "Seven of the eight primary tumor samples expressed ABL1, most of them at comparable levels to GIST882." (PMID 27965460, 2017). "Several studies reported overexpression of ABL1 along with evidence that ABL1 has tumor-promoting roles – a finding that would make these tumors amenable to treatment with ABL1 kinase inhibitors." (PMID 27965460, 2017). "The results of our study support the notion of ABL1's role as a tumor suppressor and “anti-target” in GIST." (PMID 27965460, 2017).
tumor (continued). "Even though tumour studies had shown that the NRP1 cytoplasmic domain is important for ABL1 function in fibronectin fibrillogenesis, the NRP1 cytoplasmic domain is not required for angiogenesis." (PMID 26923176, 2016). "Abl-1 also functions as a tumor suppressor in response to radiation induced DNA damage by phosphorylating p73 at Y99 and transactivating and promoting p73 dependent apoptosis." (PMID 26546517, 2015). "In melanocytes, miR-203 acts as a tumor suppressor by inducing senescence, and ABL1 is the target of miR-203, suggesting an anti-proliferative function of this miRNA." (PMID 25405349, 2014). "Of significant interest, the epigenetic silencing of the tumor suppressor miR-203 enhances the expression of the direct targets ABL1 and BCR-ABL1." (PMID 25594053, 2014). "The BCR::ABL1 (BCR—breakpoint cluster region; ABL1—ABL protooncogene 1) translocation is one of the most extensively studied abnormalities in tumor cytogenetics, resulting in the iconic Philadelphia chromosome (Ph-chromosome), which is a shortened version of chromosome 22." (PMID 39846605, 2025). "Collectively, our findings suggest that the inhibition of FOXM1 Y575 phosphorylation leads to significant suppression of tumor growth, suggesting that ABL1 kinase inhibitors could be potential clinical agents for FOXM1-overexpressing tumor therapy." (PMID 39060421, 2024). "In addition to its role in the inhibition of cell growth and induction of apoptosis, Abl1 plays a central role in the regulation of tumor development and progression." (PMID 39123481, 2024). "We then sought to verify whether ABL1 could impact FOXM1 expression in tumor cell lines with FOXM1 overexpression." (PMID 39060421, 2024). "Since, for these patients of our cohort, the real tumor load may be higher than that monitored by routine BCR::ABL1 assays (MR4.5), future follow-up may be informative." (PMID 37568730, 2023). "Altogether, we postulate that ABL1 is a tumor suppressor in myeloid malignancies." (PMID 36959186, 2023). "Therefore, the higher the tumor load, as indicated by BCR::ABL1%, the longer an administered TKI therapy will take to reduce tumor cell burden to MMR levels (=0.1% BCR::ABL1 IS)." (PMID 37174118, 2023). "A recent study showed targeting DDR1 as a therapeutic strategy against resistance to BRAF and MEK inhibitors, further confirming the significance of our findings, which suggest an unprecedented role of the interactome of DDR1, BCR, and ABL1 proteins with EGFR-ERBB2-4 signaling in tumor progression." (PMID 35664781, 2022). "We explored the relationship between ABL1 expression and tumor immunotherapy." (PMID 34484330, 2021). "In cervical cancer cells, ABL1 impacts microtubule assembly by phosphorylating PLK1, an enzyme that phosphorylates kinetochores, promoting kinetochore binding to the plus end of microtubules causing cytokinesis and tumor growth." (PMID 34022881, 2021). "We hypothesize that specific molecular targeting ABL1 expression could affect immune cell infiltration in the tumor microenvironment and improve the prognosis of patients with HCC." (PMID 34484330, 2021). "Our in vivo study also demonstrated that depletion of ABL1 reduced CRC tumor progression." (PMID 32850446, 2020). "However, data in solid tumors suggest that ABL1 can have tumor suppressive or oncogenic roles, depending on the cellular context." (PMID 32933107, 2020). "Taken together, our animal experiments demonstrated that ABL1 knockdown could inhibit CRC tumor growth in vivo." (PMID 32850446, 2020). "In the case of the pan Abl1-mutant inhibitor ponatinib, such a combination can be useful to alleviate some side effects by reducing the dose of ponatinib that is needed to inhibit tumour growth." (PMID 32380976, 2020).
tumor (continued). "Donor tumor tissue OT288 harbored an ABL1 mutation at a frequency of 6.3%, not detected in the corresponding organoid culture." (PMID 30925167, 2019). "For instance, the tumor suppressor miR-7 directly targets the ABL1 3′UTR, and its transfection in the K562 CML cell line inhibits the proliferation, increases the apoptosis and enhances sensitivity to imatinib, a tyrosine kinase inhibitor (TKI) specific for the TK domain of ABL1." (PMID 30322050, 2018). "Inhibition of ABL1 likely reduces the anti-tumor effectiveness of sole KIT inhibition in GIST." (PMID 27965460, 2017). "Moreover, an important role of the NCD in this pathway agrees with prior observations that the NCD enhances complex formation of NRP1 and VEGFR2 in VEGF165-stimulated ECs and promotes ABL1 function in tumor cells." (PMID 28289053, 2017). "The three genes that were significant for ‘Time’, ‘T2’ and the ‘T3’ contrasts in the Tumor samples (JUN, FOSB and ABL1) were selected for technical validation with Real Time PCR (RT-PCR) analysis in the same Tumor tissues belonging to the 14 different patients analyzed by microarrays." (PMID 23308215, 2013). "For instance, miR-203 methylation might contribute to tumor cell survival through upregulation of ABL1, and miR-124-1 methylation to proliferative advantage by upregulation of CDK6." (PMID 23162567, 2012). "Moreover, ABL1 inhibition effectively prevents tumor growth in vivo." (PMID 40918650, 2025). "Thus, a prominent reduction of miR-29b in CML might implicate miR-29b as a potential tumor suppressor in CML by targeting ABL1 and BCR/ABL1." (PMID 26967056, 2016). "Finally, imatinib induced reduction in tumor growth in xenografts with mutated ABL1 and simultaneous lack of response observed for xenografts with wild‐type ABL1 highlights the therapeutic potential of imatinib in NSCLC patients with ABL1 mutations." (PMID 26758680, 2016). "In addition because the primer set designed by the EAC to amplify ABL1 as control gene is located on exon a2, it may also amplify the BCR-ABL1 fusion gene transcript, underestimating the tumor load." (PMID 25594053, 2014). "To gain a more profound insight into this question in a clinically relevant context, we aim to collect tumor samples from CML patients, and explore potential correlations between cellular neddylation levels and therapeutic outcomes of BCR::ABL1-targeting TKIs." (PMID 40447744, 2025). "In particular, this is of great importance in CML routine BCR::ABL1 monitoring, as the number of BCR::ABL1 cDNA targets is considered to exactly reflect the tumor load." (PMID 37568730, 2023). "Together, these results suggest that higher absolute counts of Vδ1 and Vδ2 T cells found in patients with higher levels of tumor burden and BCR::ABL1 reflects the ongoing expansion of γδ T lymphocytes mediating antileukemic responses." (PMID 36376516, 2023). "According to the gene fusion and rearrangements of PDGFRA, PDGFRB, JAK2, FGFR1, ETV6:ABL1, and FLT3, WHO5 defined these types of neoplasms as a separate class." (PMID 37371477, 2023). "We here investigated the combination of different TKI and blinatumomab in BCR::ABL1+ and BCR::ABL1− B-ALL cell lines and primary samples regarding T cell proliferation, differentiation, cytokine release and killing of tumor cells." (PMID 35551463, 2022).
tumor (continued). "Although DNA-based approaches for KD mutation determination have the disadvantage of amplifying ABL1 from (i) non-rearranged ABL1 allele of tumor cells and (ii) the ABL1 gene of non-rearranged healthy cells, they might better represent the clonal burden and dynamics of the emerging resistant clones." (PMID 35906470, 2022). "The molecular subtype of the primary tumor played a certain role in the engraftment velocity, with mice xenografted with patient samples harboring a BCR::ABL1 translocation demonstrating the lowest mean time to experiment termination." (PMID 35011712, 2022). "Consistent with the previously reported tumour-suppressor role of PP2A, its activating drugs, such as FTY720 and OP449, have been shown to re-sensitize TKI-resistant LSCs to BCR::ABL1 inhibition by targeting the JAK2/PP2A/β-catenin pathway." (PMID 35884363, 2022). "The consequences of elevated expression of ABL1 and ABL2 for tumor progression are cell context-dependent." (PMID 34022881, 2021). "Another enriched pathway in both miRNA groups is the Hippo pathway; in MM, the YAP1 protein, which is part of the Hippo pathway, acts as a tumor suppressor, as the rescue of YAP1 has been shown to promote ABL1-dependent apoptosis in hematological malignancies." (PMID 34884950, 2021). "In both CMS-induced mice and PDX mice, exposure to CMS significantly increased ROS levels; meanwhile, both expression of ABL1 and phosphorylation of ABL1 were elevated in the hippocampus of CMS-induced mice and in the tumor tissue of PDX mice exposed to CMS." (PMID 31396300, 2019). "Especially for targeted therapy regimen, testing for presence of drugable targets in or on tumor cells is mandatory (e.g., BCR/ABL1 or HER2)." (PMID 35582146, 2019). "When all tumor samples were evaluated together the correlation of GZMH, ABL1, IL-7, LY9, IL-12, SCAMP3, and CD244 were highly significant (p < 1 × 10−6)." (PMID 29587383, 2018). "Usually, miR-203 suppresses tumour proliferation, invasion and metastasis, through the inactivation of ABL proto-oncogene 1 (ABL1) and BCR-ABL1 oncogenes." (PMID 30037059, 2018). "On the other hand, in order to examine the impact of neddylation on non-BCR::ABL1-targeting anti-tumor drugs, two chemotherapeutic agents, cisplatin and doxorubicin, were used." (PMID 40447744, 2025). "The genomic background of ABL1 is highly heterogeneous in tumor tissue but has not been well defined." (PMID 38757752, 2024). "Although normal ABL1 kinase has no direct transforming activity, its tumor promoting function has been reported before." (PMID 36959186, 2023). "Moreover, the dual inhibition of BCR::ABL1 and FLT3 via combined treatment of imatinib with quizartinib further impaired tumor growth." (PMID 37932786, 2023). "High expression levels of ABL1, FGFR2, MTOR, BRAF, and PARP1 were seen in both tumor subtypes." (PMID 36991316, 2023). "NILO only had minor effects on BCR::ABL1− cell lines, but did not inhibit tumor cell lysis of BCR::ABL1+ cell lines." (PMID 35551463, 2022). "The ABL kinases, ABL1 and ABL2, promote tumor progression and metastasis in various solid tumors." (PMID 34022881, 2021). "All CSP components interacted positively with the ABL kinase, ABL1, BCL2, and FLT3 receptors in the tumor cells, and thus may explain a possible mode of action of the extract." (PMID 34451867, 2021). "In addition, since ABL1 is the target of miR-203, treatment with imatinib and dasatinib (BCR/ABL inhibitors) prevented tumor cell growth." (PMID 35008340, 2021). "Finally, compared to macroH2A1 KD Huh-7 cells, FAK KD cells exhibited a significant reduction (p < 0.01) in the mRNA levels of tumor-promoting genes CCL2, EGF, BAX, KRT19, EGFR, NOTCH1, ABL1, and SMAD3." (PMID 33182805, 2020). "Similarly, in tumor tissues of CMS-induced mice, the expression and phosphorylation of ABL1, p-NF-κB1, p-STAT3, IL-6, IL-1β, and COX2 significantly increased." (PMID 31396300, 2019).